LINC02023 (long independently transcribed non-coding RNA 2023)
Gene: Long non-coding RNA gene on chromosome 3 (165,090,122 to 165,158,147, reverse strand). Ensembl gene ENSG00000239205.
Diseases named in the same sentence as LINC02023 in open-access papers:
LINC02023 is named in the same sentence as 1 disease in open-access papers, as found by Europe PMC text mining. Sharing a sentence is not in itself a finding about the gene and the disease.
LINC02023 shares sentences with these, for which no sentence is quoted: cancer (1 paper).